CWH43 (cell wall biogenesis 43 C-terminal homolog)
Description:
Involved in lipid remodeling during GPI-anchor maturation.
Synonyms: PGAP2IP; FLJ21511; CWH43-C
Tractability: Antibody: UniProt predicts a signal peptide or a membrane-spanning region; its Gene Ontology location is reachable by antibodies, with medium confidence.
Gene: Protein-coding gene on chromosome 4 (48,986,162 to 49,062,093, forward strand). Ensembl gene ENSG00000109182.
Subcellular location: Membrane
Subcellular location (Human Protein Atlas): Golgi apparatus; Plasma membrane
Gene Ontology:
Biological process: GPI anchor biosynthetic process
Cellular component: endoplasmic reticulum; membrane
Genetic constraint (gnomAD): Loss-of-function variants: 62 observed, 58.33 expected, observed/expected ratio (o/e) 1.06, 90% interval 0.87 to 1.31. The upper end of that interval is the gene's LOEUF score, 1.31, which puts it in group 5 of 6, group 1 being the genes least tolerant of losing a copy. Missense variants: 643 observed, 650.46 expected, observed/expected ratio (o/e) 0.99, 90% interval 0.93 to 1.05. Synonymous variants: 236 observed, 234.93 expected, observed/expected ratio (o/e) 1, 90% interval 0.9 to 1.12.
Homologues: Orthologues: chimpanzee CWH43 (99% identical), macaque CWH43 (96% identical), rabbit CWH43 (88% identical), dog CWH43 (87% identical), guinea pig CWH43 (84% identical), pig CWH43 (84% identical), mouse Cwh43 (83% identical), rat Cwh43 (83% identical).
Diseases named in the same sentence as CWH43 in open-access papers:
CWH43 is named in the same sentence as 16 diseases in open-access papers, as found by Europe PMC text mining. Sharing a sentence is not in itself a finding about the gene and the disease. The quoted sentences say what the papers report.
colorectal cancer (4 papers, 2014 to 2023). A primary or metastatic malignant neoplasm that affects the colon or rectum. "A recent study identified CWH43 as a prognosis-related gene in colorectal cancer (CRC), but little is known about its function." (PMID 37359529, 2023). "One meta-analysis also showed that CWH43 was differentially expressed between colorectal cancer and normal samples." (PMID 33717664, 2021).
gastric cancer (3 papers, 2021 to 2023). A primary or metastatic malignant neoplasm involving the stomach. "Another pinpointed CWH43 as a central gene in gastric cancer via weighted gene co-expression network analysis." (PMID 37894942, 2023). "In this study, three biomarkers, ADH7, CWH43 and SCNN1B, were included in the model that used multiple bioinformatics methods to screen for gastric cancer." (PMID 37359529, 2023). "It was confirmed that ADH7, CWH43 and SCNN1B all showed low expression in gastric cancer cells (p < 0.05)." (PMID 37359529, 2023).
Hydrocephalus (3 papers, 2021 to 2023). Hydrocephalus is an active distension of the ventricular system of the brain resulting from inadequate passage of CSF from its point of production within the cerebral ventricles to its point of absorption into the systemic circulation. "Our studies in mice harboring heterozygous iNPH-associated mutations in either CWH43 or AK9 show that these mutations can cause communicating hydrocephalus in an autosomal dominant manner." (PMID 38100419, 2023). "We find that iNPH-associated mutations affecting two of these genes, AK9 and CWH43, alter ependymal motile cilia function and cause an iNPH-like syndrome in mice that is characterized by communicating hydrocephalus and balance impairment." (PMID 38100419, 2023). "Mice that are heterozygous for iNPH-associated CWH43 or AK9 mutations develop an iNPH-like syndrome that is characterized by grossly normal appearance and behavior, normal lifespan, age-dependent communicating hydrocephalus, and impairments of gait or balance." (PMID 38100419, 2023). "Mice heterozygous for CWH43 deletion appeared grossly normal but displayed hydrocephalus, gait and balance abnormalities, decreased numbers of ependymal cilia, and decreased localization of glycosylphosphatidylinositol‐anchored proteins to the apical surfaces of choroid plexus and ependymal cells." (PMID 33459505, 2021). "Two deletions in CWH43 which regulates the membrane targeting of glycosylphosphatidylinositol-anchored proteins were identified in 8 of 53 iNPH patients (15 %), and CWH43 mutant mice exhibited communicating hydrocephalus with gait and balance dysfunction." (PMID 33874972, 2021). "Several mutations in Ccdc39, Celsr2, Celsr3, Cetn2, Dvls, FoxJ1, Hydin, Mdnah5, Pkd1, Tg737, Daple, Dnah14, Cfap43 and Cwh43 genes, which were related to the structure or function of motile cilia on ependymal cells, have been reported to develop hydrocephalus in animal models." (PMID 33874972, 2021).
astrocytoma (2 papers, 2023 to 2024). "Interestingly, there were two CpGs with decreased 5-hmC levels and increased gene expression in astrocytoma, ependymoma, and glioneuronal/neuronal tumors: cg18280362 located in the promoter region of CWH43 and cg08278401 located in the promoter region of LRRC72." (PMID 36909536, 2023).
colorectal tumor (2 papers, 2014 to 2021). "Cell Wall Biogenesis 43 C-Terminal Homolog (CWH43) has been reported to be downregulated in colorectal tumor tissues, although little is known about its function." (PMID 34944753, 2021). "The expression of CWH43 was downregulated in colorectal tumor tissues (fold change = −4.59)." (PMID 24959000, 2014).
cancer (5 papers, 2015 to 2024). A tumor composed of atypical neoplastic, often pleomorphic cells that invade other tissues. "This implies that the tumor-associated downregulation of CWH43 may instigate cancer cells towards EMT, consequently fostering metastasis." (PMID 37894942, 2023). "To further validate CWH43’s influence on cancer cell proliferation, we engineered HT-29 cells with reduced CWH43 levels (CWH43-KD) and HCT116 cells with elevated CWH43 expression (CWH43ov)." (PMID 37894942, 2023). "To explore the enigmatic function of CWH43 in the development of cancer, we delved into its downstream regulatory mechanisms and linked genes in CRC." (PMID 37894942, 2023). "Relative to the normal esophageal epithelium, 392 (46.3%) and 494 (52.1%) cancer-specific SEs were recovered in the EC and LNC H3K27ac profiles, respectively, and these SEs were enriched with cancer-associated genes or oncogenes, such as CCND125,26, CWH43, ANO1, and CXCR4." (PMID 34294701, 2021). "However, the specific role that CWH43 plays in cancer progression remains ambiguous." (PMID 37894942, 2023). "Several top-ranking genes, such as MEIS1, ZDHHC11, CWH43, TTC12, and CDH22, have been supported by recent studies as playing roles in various cancers and aging-related processes." (PMID 39499149, 2024). "Leveraging data from The Cancer Genome Atlas (TCGA), our Gene Set Enrichment Analysis (GSEA) indicated a positive relationship between low CWH43 expression and the activation of the epithelial–mesenchymal Transition (EMT) pathway." (PMID 37894942, 2023).
tumor (3 papers, 2023 to 2025). "Importantly, inhibition of TTK counteracted the tumor-promoting effects caused by CWH43 downregulation." (PMID 37894942, 2023). "Highly regulated DEGs in the SPF DOWN cluster include genes that have been associated with tumour suppression and CRC (Meg3, Cwh43, Naprt), lipid metabolism and detoxification (Ces1f) and bactericidal/antimicrobial activity (Iapp)." (PMID 40890536, 2025). "Though we have unveiled CWH43’s tumor-suppressing role in CRC and its potential interaction with TTK, the exact mechanisms remain elusive." (PMID 37894942, 2023). "Our study unearthed diminished levels of CWH43 expression in CRC tumor samples, sourced from public databases." (PMID 37894942, 2023). "This suggests that CWH43’s tumor-suppressing potential might act via TTK modulation." (PMID 37894942, 2023). "Our findings propose that the decreased expression of CWH43 amplifies TTK-mediated cell cycle activities, thus encouraging tumor growth." (PMID 37894942, 2023). "Furthermore, suppressing CWH43 amplified CRC cell growth and tumor expansion in mice, whereas its increased expression curtailed CRC cell viability." (PMID 37894942, 2023).
metabolic disorders (1 paper, 2019). "Considering that sensitivities to nutrient deficiencies and lipid accumulation in cwh43 mutant are clearly rescued by Pmr1 deletion, these metabolic disorders may be caused by Pmr1-mediated Mn2+ transport into the ER." (PMID 31201205, 2019).
CWH43 also shares sentences with these, for which no sentence is quoted: ependymoma (2 papers); neuronal tumor (2); age (1); breast carcinoma (1); communicating hydrocephalus (1); Ewing sarcoma (1); fibromatosis (1); leukemia (1).